INS (insulin)
Diseases named in the same sentence as INS in open-access papers (continued):
Sharing a sentence is not in itself a finding about the gene and the disease.
type 2 diabetes (continued). "Type 2 diabetes (T2D) is characterised by the loss of first-phase insulin secretion." (PMID 38677509, 2024). "Additionally, MVPA increases insulin sensitivity and glucose uptake, which lowers the risk of developing type 2 diabetes." (PMID 39712192, 2024). "In conclusion, our modelling found that replacing red meat, and possibly processed meat, with legumes, nuts and seeds, or wholegrains (or a combination thereof) predicted higher insulin sensitivity in Australian adults, implying a lower risk of type 2 diabetes." (PMID 37981891, 2024). "Similarly, CPAP use has been linked to improvements in insulin sensitivity and lipid profiles, reducing the risk for metabolic syndrome and type 2 diabetes." (PMID 38672697, 2024). "The more favorable post-ingestive profile of glucose and insulin after consuming pecans suggests that they may be beneficial to individuals at risk of developing metabolic dysfunction and type 2 diabetes." (PMID 38999832, 2024). "Insulin secretion by pancreatic β cells has a pivotal role in maintaining glucose homeostasis, and impaired insulin secretion is a hallmark of β cell failure in type 2 diabetes." (PMID 37945898, 2024). "However, there is no longer any doubt that environmental contaminants such as BPA and TCDD are strong risk factors in the development of type 2 diabetes, notably through an alteration in the process of insulin secretion by β‐pancreatic cells." (PMID 39218795, 2024). "It has been consistently shown that diets high in fats increase the risk of type 2 diabetes through impaired glucose tolerance and the binding of insulin to its receptors, resulting in altered glucose transport and the accumulation of triglycerides in skeletal muscles." (PMID 38257161, 2024). "A vast number of epidemiological, genetic, rodent, and human in vivo and in vitro studies have investigated the putative role of action/lack of action of IL-6 in the pathogeneses underlying obesity, insulin resistance, β-cell destruction, type 1 diabetes, and type 2 diabetes." (PMID 38504163, 2024). "Experimental studies in animals and humans demonstrated that exposure to light patterns that disrupt circadian rhythms caused reduced glucose tolerance, altered insulin secretion and lipid profiles, and weight gain, supporting the role of light exposure in the pathogenesis of type 2 diabetes." (PMID 39070751, 2024). "This is because increased visceral adipose tissue is associated with metabolic abnormalities, and myocardial infarction (MI), including decreased glucose tolerance, reduced insulin sensitivity and adverse lipid profiles, risk factors for type -2 diabetes and deaths." (PMID 38295048, 2024). "This type of diet provides several potential advantages on the glycemic and lipid profile: The high fiber content from fruits, vegetables, and whole grains aids in regulating blood sugar levels, enhancing insulin sensitivity, and reducing the risk of type 2 diabetes." (PMID 39519532, 2024). "The favorable effect of BMI-C3 could be through increasing skeletal muscle mass, which has been associated with decreased type 2 diabetes risk potentially via increased insulin sensitivity, improved glucose metabolism, or acting as a sink for glucose." (PMID 38530928, 2024). "It has been hypothesized that chlorogenic acid from coffee could have a favorable effect on type 2 diabetes risk by reducing glucose levels in the blood and increasing insulin sensitivity." (PMID 38571923, 2024). "Type 2 diabetes (T2D) is one of the most common metabolic disorders primarily caused by a combination of two main factors; defective insulin secretion by pancreatic β‐cells and the failure of insulin‐sensitive tissues to respond to insulin." (PMID 39676616, 2024).
type 2 diabetes (continued). "Metformin, a biguanide used to treat type 2 diabetes, was found to reduce the risk of dementia, cancer, and other age-related disorders by reducing insulin and IGF-1 levels, inhibiting the mTOR pathway, blocking mitochondrial function, reducing oxidative damage, and activating the AMP kinase." (PMID 39123408, 2024). "Higher adiposity increases type 2 diabetes risk via different mechanisms (e.g., cholesterol pathways or inflammation) but decreases risk via other mechanisms (lower liver fat and improved insulin sensitivity, or increased body size and enhanced muscle quality)." (PMID 38530928, 2024). "Wang and colleagues found that the A/A genotype of NRF2 rSNP-617 was associated with significantly worse β-cell function and insulin sensitivity compared with the C/C genotype in a cohort of Chinese individuals composed of patients with newly diagnosed type 2 diabetes and healthy controls." (PMID 37962746, 2024). "In addition, low-to-moderate alcohol consumption was suggested to improve insulin sensitivity and associated with decreased incidence of type 2 diabetes." (PMID 39518680, 2024). "SEM promotes insulin uptake in peripheral tissues, resulting in weight loss, reduced risk of hepatic steatosis, and increased lipolysis, making them beneficial for patients with type 2 diabetes and obesity." (PMID 38921025, 2024). "Given the growing promotion of plant-based eating patterns, coupled with advice to limit red and processed meat intake and favour plant-based sources of protein, it is important to understand how the resulting food substitutions associate with insulin resistance, a risk factor for type 2 diabetes." (PMID 37981891, 2024). "Finally, in the multivariate analysis of PSC, after correction for genetically fasting glucose/fasting insulin/type 2 diabetes, the suggestive association of HbA1c (OR = 0.369, 95%CI 0.138–0.986, P = 0.046) with a decreased risk of PSC remained significant." (PMID 38704596, 2024). "This suggests that a higher abundance of Terrisporobacter may be associated with lower insulin secretion in individuals with type 2 diabetes." (PMID 39287885, 2024). "Emerging evidence suggests that trans fats may impair insulin sensitivity, increasing the risk of developing type 2 diabetes." (PMID 39796335, 2024). "Some studies indicate that trans fats may negatively affect pancreatic function, further exacerbating the risk of type 2 diabetes by impairing insulin production." (PMID 39796335, 2024). "Insulin pharmacotherapy is associated with an increased risk for hypoglycaemia and weight gain; thus, its use in type 2 diabetes is typically recommended in later stages, when hyperglycaemia cannot be adequately controlled with other treatments, or when they are contraindicated." (PMID 39639300, 2024). "Dragon fruit’s ability to increase SCFA production—especially the production of butyric acid, which is linked to reduced inflammation and improved insulin sensitivity—suggests that it could help manage metabolic disorders like obesity and type 2 diabetes." (PMID 39683835, 2024). "Additionally, it has been linked to improved insulin sensitivity and reduced risk of type 2 diabetes and supports the immune system by enhancing immune function and modulating inflammatory responses." (PMID 39410059, 2024). "In the pathogenic progression of type 2 diabetes, the most important determining step could be the β-cell failure to compensate for the elevated insulin need." (PMID 38297165, 2024). "Depletion of PUFAs may lead to a depletion of these oxylipins to cause impairments of insulin action and endothelial function, major risk factors for type 2 diabetes and CVD." (PMID 39201497, 2024). "By improving insulin sensitivity, irisin can help in better utilisation of glucose by tissues, thereby reducing blood sugar levels and lowering the risk of insulin resistance and type 2 diabetes." (PMID 39683426, 2024).
type 2 diabetes (continued). "Moreover, MASLD and MASH are highly associated (50%–80%) with impaired insulin response, type 2 diabetes, dyslipidaemia, hypertriglyceridemia, hypertension, and more than 90% of obese patients with type 2 diabetes have MASH." (PMID 39086662, 2024). "Studies on PPAR-γ knockout mice have shown that PPAR-γ is crucial for maintaining normal insulin sensitivity, glucose metabolism, and lipid metabolism homeostasis and that its abnormal expression is closely associated with the development of type 2 diabetes, obesity, and cardiovascular disease." (PMID 38159176, 2024). "Thus, caution is advised when considering neddylation inhibitors as a treatment option for cancer patients, particularly those presenting with insulin signaling dysregulations linked to conditions like obesity-related type 2 diabetes or hyperinsulinemia." (PMID 38272982, 2024). "In 2011, professor Barbara Corkey hypothesized that that excessive β-cell secretory insulin responses, possibly to environmental factors, may be a major cause of type 2 diabetes." (PMID 38791525, 2024). "Thus, further work examining how exercise vs. diet mediate improvements in insulin resistance and cardiometabolic health is warranted to optimize risk reduction for Type 2 diabetes and cardiovascular disease." (PMID 38561248, 2024). "An immune-mediated type 1 diabetes, which is characterized by an absolute insulin deficiency, is considerably more frequently diagnosed in children and adolescents than type 2 diabetes, which is caused by impaired insulin secretion or a defect in insulin action." (PMID 38386644, 2024). "Although its pathogenesis remains largely unclear, hyperglycemic insults, along with dyslipidemia, atherosclerosis, and impaired insulin action (in the case of type 2 diabetes), cause a range of metabolic abnormalities in neurons, Schwann cells, and vascular endothelial cells." (PMID 39906036, 2024). "In addition to killing beta cells, these ROS also stop the release of insulin, which causes hyperglycemia and type 2 diabetes." (PMID 39055230, 2024). "Although they add almost no calories, studies have shown that artificial sweeteners may affect metabolism by stimulating insulin secretion and changing the intestinal microbiota, increasing the risk of metabolic syndrome and type 2 diabetes." (PMID 39767777, 2024). "A typical hallmark of type-2 diabetes is linked to the ability of certain lipids to impair insulin signalling, whereas increased lipogenesis could contribute to the de novo synthesis of fatty acids." (PMID 39201610, 2024). "Type-2 diabetes is associated with an increased risk of dementia, and the underlying mechanism might involve abnormal insulin signaling in the brain." (PMID 38029396, 2024). "At a certain amount of (ectopic) fat accumulation in the liver and pancreas (and partly due to the negative effects of fat on hepatic insulin sensitivity/actions, pancreatic insulin secretion and muscle insulin sensitivity), prediabetes/type 2 diabetes will develop in susceptible individuals." (PMID 38791525, 2024). "Its expression is associated with insulin-stimulated glucose uptake and type 2 diabetes." (PMID 39478854, 2024). "Also, high-protein diets can enhance insulin sensitivity and glucose metabolism, reducing the risk of type 2 diabetes or metabolic syndrome." (PMID 39452682, 2024). "Higher levels of PFAS have been associated with type 2 diabetes, increased glucose and insulin levels in pregnancy and may play an important role in GDM development." (PMID 37704943, 2023). "Hypoglycemic conditions, induced by injecting too much insulin, can result in a life-threatening coma and are a constant risk for patients living with T1D and a practical cure that would alleviate the risks and concerns of current insulin therapy is desperately needed." (PMID 36899834, 2023).
type 2 diabetes (continued). "Not all PDs, but second-generation antipsychotics, cause weight gain and reduce insulin sensitivity and glucose tolerance, which may lead to the development of type 2 diabetes." (PMID 37476651, 2023). "PRS could be associated with insufficient insulin secretion, commonly seen in Asians with type 2 diabetes, and it suggests that height-related genetic variants could be associated with insulin secretion." (PMID 37049604, 2023). "Type 2 diabetes is characterized by an elevated blood glucose level, a chronic hyperglycemic state caused by a combination of pancreatic β-cell loss through apoptosis and insulin resistance in peripheral tissues, such as skeletal muscle." (PMID 37240215, 2023). "Moreover, it has been previously shown that WSCD2 is functionally associated with type 2 diabetes and positively correlated with insulin secretion." (PMID 37433298, 2023). "Type 2 diabetes tends to occur in adults because of a continuous increase in the blood glucose level, which is caused by insufficient insulin secretion or difficulty in the use of insulin for various reasons." (PMID 36755915, 2023). "Thus, loss of adipose HK2 causes selective insulin resistance and thereby contributes to the pathogenesis of type 2 diabetes." (PMID 36920797, 2023). "Diabetes is a metabolic disease characterized by high blood glucose levels due to dysfunction in the body’s glucose-handling mechanism, often caused by insulin secretion defects or impaired biological function, or both, and is generally classified into type 1 and type 2 diabetes (T1/2D)." (PMID 38003338, 2023). "The deficiency of insulin-mediated glycogen synthesis is one of the main causes of type 2 diabetes." (PMID 37108143, 2023). "Even in healthy individuals with normoglycaemia, those with a greater glycaemic response after feeding have reduced insulin sensitivity and impaired beta-cell function and, therefore, are at higher risk of developing type 2 diabetes (T2D) and cardiovascular disease (CVD)." (PMID 37177452, 2023). "Importantly, aberrations of both insulin and leptin signal transduction are implicated in serious metabolic disorders such as type 2 diabetes (T2DM) and obesity." (PMID 37298571, 2023). "On the other hand, the case of advanced type 2 diabetes might cause an insulin shortage, necessitating the addition of insulin to the therapeutic regimen." (PMID 36769081, 2023). "Type 2 diabetes mellitus is a complicated metabolic illness that not only causes hyperglycemia but is also accompanied by other metabolic issues including insulin resistance, decreased insulin secretion, hypertension, dyslipidemia, and more." (PMID 37908927, 2023). "Indeed, epigenetic mechanisms have been involved in the regulation of glucose metabolism insulin signaling, and the risk of type 2 diabetes mellitus." (PMID 37836535, 2023). "One well documented health risk associated with increased insulin levels is type 2 diabetes." (PMID 37854186, 2023). "Emerging evidence has demonstrated the key role of phosphatidylethanolamine in the insulin signaling pathway, and it was suggested that increased phosphatidylcholine/phosphatidylethanolamines ratio was associated with reduced insulin sensitivity and elevated among patients with type 2 diabetes." (PMID 36927416, 2023). "In type 1 diabetes (T1D), β-cells, which are 55% of the human islet cell population, are ablated due to autoimmunity, whereas type 2 diabetes (T2D) is linked to damage of β-cells and reduction in their mass due to insulin resistance exhibited by peripheral tissues." (PMID 37645413, 2023). "As such, this hormone may be a marker of insulin sensitivity (its low level is considered an independent risk factor for type 2 diabetes), and it is also useful in determining the risk of cardiovascular disease in humans." (PMID 38004222, 2023).
type 2 diabetes (continued). "In our exploratory pilot cohort of ICU patients with type 2 diabetes managed according to a liberal glucose control protocol, treatment with empagliflozin reduced insulin requirements and was associated with a significantly greater increase in sodium and chloride levels and urinary output." (PMID 37194077, 2023). "In addition, it was established an association of genetic variations in the WFS1 locus with reduced GLP-1-induced insulin secretion and a higher risk of type 2 diabetes." (PMID 37333802, 2023). "Stearoylcarnitine is an important long-chain ACs, which has been previously confirmed to be elevated in the blood of obese individuals and accumulate in β cells of subjects with type 2 diabetes, leading to insulin arrest and energy deficiency in key energy pathways." (PMID 37215555, 2023). "Sex hormone-binding globulin prevents insulin resistance to endoplasmic reticulum stress in hepatocytes, reducing type 2 diabetes and counteracting the development of obesity caused by high-fat diets, and sex hormone-binding globulin improves insulin sensitivity by stimulating hepatocytes." (PMID 37600949, 2023). "However, they found that low vitamin D levels were associated with a higher risk of developing type 2 diabetes, as vitamin D helps to improve sensitivity to insulin." (PMID 37351236, 2023). "Furthermore, loss of asna-1 causes insulin secretion defects in C. elegans and loss of Get3 in pancreatic β cells in mice leads to type 2 diabetes." (PMID 36939052, 2023). "Furthermore, metabolic changes in choline are related to a higher risk of type 2 diabetes due to impaired insulin sensitivity." (PMID 37765098, 2023). "Consuming LC ω-3 PUFAs might also be associated with increased insulin sensitivity and decreased risk of type 2 diabetes." (PMID 37031750, 2023). "Adiponectin is associated with insulin sensitivity and a reduction in obesity and type 2 diabetes." (PMID 37760423, 2023). "For instance, the inclusion of fasting insulin in addition to fasting glucose or HbA1c in asymptomatic individuals could potentially identify individuals at risk of type 2 diabetes years before disease initiation." (PMID 38115031, 2023). "It would be interesting to analyse the type 2 diabetes genetic risk in these patients and carry out long-term follow-up with physiological studies of insulin secretion to better understand the aetiology of diabetic ketoacidosis in autoantibody-negative individuals." (PMID 36355183, 2023). "However, only a few studies have been conducted on the risk of requiring insulin treatment and complications related to newly developed type 2 diabetes among patients with cancer based on a nationwide population." (PMID 36831436, 2023). "Misfolding of the insulin prohormone, proinsulin (PI), is increasingly appreciated as an early pathogenic event in type 2 diabetes (T2D) when a mismatch is reached between PI biosynthetic demand, typically increased due to insulin resistance, and folding capacity." (PMID 36671537, 2023). "IGF2BP2 is associated with impaired insulin secretion and human type 2 diabetes." (PMID 37373054, 2023). "In type 2 Diabetes, β-cell failure is caused by loss of cell mass, mostly by apoptosis, but also by simple dysfunction (downregulation of specific gene expression, decline of glucose-stimulated insulin secretion)." (PMID 37306934, 2023). "Besides, sleep loss impairs glucose homeostasis and insulin sensitivity, leads to health outcomes related to metabolic systems, such as obesity and type 2 diabetes, both plays an important role in development of CCVD." (PMID 37003977, 2023). "Moreover, a study indicated that diabetic retinopathy is an independent risk factor for cataract formation in patients with type 2 diabetes, alongside BMI, HbA1c, and insulin usage." (PMID 38051579, 2023).